SOX4 (SRY-box transcription factor 4)
Diseases named in the same sentence as SOX4 in open-access papers (continued):
Sharing a sentence is not in itself a finding about the gene and the disease.
cervical carcinoma (27 papers, 2015 to 2026). A carcinoma arising from either the exocervical squamous epithelium or the endocervical glandular epithelium. "Given that cisplatin preferentially targets highly proliferating cells, SOX4-driven metabolic deceleration enables cervical cancer cells to evade cisplatin-mediated cytotoxicity." (PMID 41832199, 2026). "Together, these findings demonstrate that SOX4 enhances cisplatin resistance in cervical cancer through SIRT1-upregulated suppression of glycolysis." (PMID 41832199, 2026). "Overexpression of SOX4 markedly suppressed glycolytic activity in cervical cancer cells and induced cisplatin resistance by inhibiting both the intrinsic and extrinsic apoptotic pathways." (PMID 41832199, 2026). "Sox4 was identified as a putative target of miR-133a and was released by the action of lncRNA, with the researchers concluding that the enhanced level of Sox4 led to the progression of cervical carcinoma in mice." (PMID 38474419, 2024). "Past studies have indicated that has_circ_0008285 can competitively bind to miR-211-5p as a miRNA sponge, release SOX4, and promote the self-renewal and proliferation of cervical cancer cells." (PMID 33879262, 2021). "Recent mechanism experiments revealed that knockdown of NEAT1 inhibited cervical cancer development through repressing cell proliferation, migration, and invasion and also inducing cell apoptosis by regulating the miR-133a/SOX4 pathway." (PMID 32151082, 2020). "It has been reported that SOX4 contributes to the progression of cervical cancer and the resistance to the chemotherapeutic drug through ABCG2." (PMID 32943989, 2020). "Although our previous work identified that SOX4 promotes cisplatin resistance in cervical cancer cells, the underlying mechanism has not been fully elucidated." (PMID 41832199, 2026). "hsa_circ_0008285 facilitates the progression of cervical cancer by targeting miR-211-5p/SOX4 axis." (PMID 40427372, 2025). "Silencing of circCCNB1 repressed cervical cancer development by increasing SOX4 expression." (PMID 39469202, 2024). "LncRNA JPX can promote cervical cancer progression by regulating the miR-25–3p/SOX4 axis." (PMID 34026852, 2021). "In addition, circUBAP2 modulates cancer cell malignancy through the miR-641/YAP1 axis and miR-361-3p/SOX4 axis in osteosarcoma and cervical cancer, respectively." (PMID 33707417, 2021). "LINC01305 is able to repress the development of cervical cancer by regulating miR-129-5p and Sox4." (PMID 34692852, 2021). "Our study demonstrates that JPX promotes cervical cancer progression through modulating the miR-25-3p/SOX4 axis, and may serve as a potential target for CC therapy." (PMID 32943989, 2020). "It has been reported that SOX4 contributes to the progression of cervical cancer." (PMID 32943989, 2020). "In conclusion, we found that SOX4 was upregulated in cervical cancer cells." (PMID 26583330, 2015). "In addition, SOX4 involvement in drug resistance has been described in colon and cervical cancer." (PMID 36766786, 2023). "In cervical cancer, SNHG5 represses miR-132 and upregulates SOX4, thereby promoting tumor proliferation and invasion, underscoring miR-132 as a shared regulatory node of SNHG5 across tumor contexts." (PMID 41550840, 2026). "that NEAT1 via targeting SRY-Box transcription factor 4 (SOX4) as a downstream target of miR-133a can induce colony formation, cell proliferation, migration, and invasion in cervical cancer cells." (PMID 37310654, 2023). "Concerning cervical cancer, hsa-miR-133a appears downregulated by NEAT1, which in turn results in upregulation of SOX4 and cervical cancer progression." (PMID 35008626, 2021). "For example, miR-138 suppressed cell proliferation, invasion and migration as a tumor suppressor gene in cervical cancer by targeting H2AX, and in ovarian cancer cells via SOX4." (PMID 33919449, 2021).
colon carcinoma (24 papers, 2008 to 2024). "This study investigated the associations between nuclear SOX4 expression and clinicopathologic parameters, and evaluated the significance of nuclear SOX4 in predicting the prognosis for patients with colon cancer." (PMID 23826209, 2013). "Nuclear SOX4 expression in colon cancer and its association with clinicopathologic parameters." (PMID 23826209, 2013). "Rescue assays validated that SOX4 elevation reversed the suppressive role of LEMD1 deletion in the development of colon cancer and the expression of p-PI3K and p-AKT." (PMID 35294319, 2022). "Collectively, LEMD1 induced by SOX4 drove the progression of colon cancer by activating PI3K/Akt signaling." (PMID 35294319, 2022). "In the same way, the experimental results in this study also indicated that SOX4 was distinctly overexpressed in colon cancer tissues and cells." (PMID 35294319, 2022). "Functional experiments also confirmed that the suppressive role of LEMD1 knockdown in the proliferation, migration, invasion and angiogenesis of colon cancer cells was reversed by elevation of SOX4." (PMID 35294319, 2022). "Intriguingly, the high expression of SOX4 in colon cancer tissues was highlighted by GEPIA database." (PMID 35294319, 2022). "The SOX-4 transcription factor has been shown to enhance the cell proliferation in SW480 colon cancer cell lines through stabilization of β-catenin activated aberrant Wnt signaling pathways." (PMID 34157052, 2021). "The study on colon cancer, where the nuclear SOX-4 overexpression was closely corresponded with tumor invasion and distant metastasis, has been proved the crucial role of SOX-4 protein in tumor development and EMT initiation." (PMID 34157052, 2021). "The immunoblotting results confirmed that nuclear SOX4 expression was higher in colon cancer cells than in normal colon cells." (PMID 23826209, 2013). "Univariate Cox regression analysis showed that overexpression of nuclear SOX4 was a clear prognostic marker for colon cancer (P = 0.001)." (PMID 23826209, 2013). "Expression levels of nuclear SOX4 were analyzed by immunohistochemistry; the data comprised colon tissues from 263 patients with colon cancer." (PMID 23826209, 2013). "In summary, this study provided evidence for the clinical significance of overexpressed SOX4 in patients with colon cancer." (PMID 23826209, 2013). "Western blot analysis also demonstrated that the expression of SOX4 was substantially increased in colon cancer cells and tissues when compared with normal cells and tissues." (PMID 23826209, 2013). "In the present study, we assessed the expression levels of nuclear SOX4 in colon tissues obtained from 263 patients with colon cancer." (PMID 23826209, 2013). "Because our patient group was small, future studies should include a larger colon cancer patient group to elucidate the prognostic significance of nuclear SOX4 in this disease." (PMID 23826209, 2013). "Our finding also showed that overexpression of nuclear SOX4 in colon cancer tissues was closely correlated with tumor invasion and metastasis." (PMID 23826209, 2013). "Our study was the first to show that overexpression of nuclear SOX4 can predict poorer outcomes for patients with colon cancer." (PMID 23826209, 2013). "Overexpression of nuclear SOX4 appears to be a useful marker to predict outcomes in patients with colon cancer who have received surgical resection of the tumor." (PMID 23826209, 2013). "Fendrr transcription levels are negatively correlated with SOX4 protein levels in colon cancer; SOX4 protein is one of the binding targets of Fendrr, and Fendrr-mediated SOX4 inhibition may be essential in reducing colon cancer progression." (PMID 36719027, 2023). "Meanwhile, the overexpression of SOX4 predicts a poor outcome of colon cancer patients." (PMID 35294319, 2022). "Besides, SOX4 expression in colon cancer tissues and the correlation between SOX4 and LEMD1 were examined using the GEPIA database." (PMID 35294319, 2022).
colon carcinoma (continued). "Taken together, LEMD1 mediated by SOX4 drove the progression of colon cancer." (PMID 35294319, 2022). "A great number of reports have also claimed that SOX4 functions as a promoter in colon cancer." (PMID 35294319, 2022). "The subsequent experiments were performed to further investigate whether LEMD1 affected colon cancer angiogenesis was regulated by SOX4." (PMID 35294319, 2022). "Briefly, LEMD1 mediated by SOX4 exacerbated angiogenesis in colon cancer." (PMID 35294319, 2022). "In particular, another member of the SOXC family also expressed in colon cancer, SOX4, is a positive cofactor for WNT-TCF signaling, raising the possibility that SOX12 could share this activity." (PMID 24920608, 2014). "We found no published reports discussing the prognostic significance of SOX4 in human colon cancer." (PMID 23826209, 2013). "Overexpression of nuclear SOX4 may be used as a marker to predict the outcome of patients with colon cancer." (PMID 23826209, 2013). "Our findings indicate that targeting SOX4 might provide a new therapeutic modality for the treatment of colon cancer." (PMID 23826209, 2013). "Thus, patients with colon cancer who display overexpression of nuclear SOX4 should be followed up carefully." (PMID 23826209, 2013). "Anyway, whether SOX4 binds to LEMD1 in colon cancer remains elusive." (PMID 35294319, 2022). "It is noteworthy that SOX4 may serve as a prognostic factor in colon cancer." (PMID 35294319, 2022). "The regulatory function of TEAD4, TCF3, ETV4, SOX4, and FOXM1, over other key TFs and common DEGs, was highlighted in colon cancer, establishing key co-regulatory complexes." (PMID 39228892, 2024). "Expression of SOX4 or PIK2C2B leads to MGH-CP1 resistance, with SOX4 showing strong effects in Huh7 cells, while PIK2C2B is more effective in colon cancer cell lines (HCT116 and DLD1)." (PMID 36347861, 2022). "Correlation analysis of SOX4 and LEMD1 uncovered that SOX4 had a positive correlation with LEMD1 in colon cancer." (PMID 35294319, 2022). "Commonly repressed genes included the colon and colon cancer stem cell genes ASCL2 and LGR5 as well as EPHB2, SOX4 and P21, all as compared with control cells after normalization with housekeeping genes." (PMID 24920608, 2014). "Whereas SOX4 knockdown resulted in apoptosis of ACC3 adenoid cystic carcinoma cells, SOX4 overexpression promoted cell cycle arrest and apoptosis of HCT116 colon carcinoma cells." (PMID 23285187, 2012). "It has been reported that other SOX family members, such as SOX4 and SOX9, induce apoptosis in bladder, prostate and colon carcinomas, being consistent with our finding." (PMID 18268498, 2008). "In colon cancer, BMP7 is common overregulated gene, as are TGFB2, TGFBI, and TGIF2, which might be involved in the regulation of SOX4." (PMID 39228892, 2024). "All in all, SOX4 could bind to LEMD1 promoter and positively regulated LEMD1 expression in colon cancer cells." (PMID 35294319, 2022). "Meanwhile, SOX4 and LEMD1 had a positive correlation in colon cancer tissues and cells." (PMID 35294319, 2022). "To date, the prognostic significance of nuclear SOX4 expression levels in human colon cancer has not been established." (PMID 23826209, 2013). "Other SOX factors, such as SOX4 and SOX9, have been reported as tumour-suppressive proteins in bladder, breast, prostate and colon carcinomas." (PMID 18268498, 2008). "Therefore, it is not surprising that the expression of SOX4 is increased in various malignancies, including breast, prostate, stomach, and colon cancer, and that it acts as an oncogene which was not confirmed in the present study." (PMID 39028420, 2024).
pancreatic cancer (24 papers, 2012 to 2025). "Conversely, in pancreatic cancer, miR-30d suppresses the proliferation and invasiveness of the cancer by targeting the SOX4/PI3K-AKT axis, with its downregulation linked to poor patient prognosis." (PMID 40004152, 2025). "The level of miR-129-2 or miR-335 was decreased in most pancreatic carcinoma samples compared to that of tumor-uninvolved tissues in the same patient and was associated with concomitant increased mRNA levels of SOX4." (PMID 23251334, 2012). "SOX4 may promote the occurrence of the high-risk C2 subtype of pancreatic cancer by regulating MAPK1-IQGAP1 phosphorylation modification." (PMID 38943117, 2024). "Our findings further show that miR-30d and SOX4 may be valuable diagnostic markers for predicting the prognosis and recurrence of pancreatic cancer patients." (PMID 33824274, 2021). "In cell experiments, pancreatic cancer cells were grouped, and the expression levels of SOX4, MAPK1, and the phosphorylation level of IQGAP1 were detected by RT-qPCR and Western blot experiments." (PMID 38943117, 2024). "The miR-30d-5p mimic was reported to reduce cell proliferation by inhibiting the PI3K/AKT pathway through SOX4 in pancreatic cancer cells." (PMID 36140161, 2022). "Utilizing mesothelin-redirected CAR-T cells in pancreatic cancer, CAR dysregulation was found to be associated with a CD8+ T-to-NK-like T cell transition, as driven by SOX4 (SRY-Box Transcription Factor 4) and ID3." (PMID 35008832, 2021). "miR-30d inhibits pancreatic cancer cell proliferation, migration, and invasion in association with the PI3K-AKT signaling pathway by targeting SOX4." (PMID 33824274, 2021). "Kaplan–Meier survival analysis of patients in GSE62165 showed that pancreatic cancer patients with high SOX4 expression had worse OS compared with patients with low SOX4 expression." (PMID 33824274, 2021). "Both CCK-8 and colony formation assays showed that while overexpression of miR-30d inhibited the proliferation abilities of pancreatic cancer cells, these effects were partially reversed after SOX4 overexpression." (PMID 33824274, 2021). "In these databases, a positive correlation between SOX4 expression and poor patient survival was observed in colon, liver, lung, and pancreatic cancers, as well as sarcoma." (PMID 34442467, 2021). "IHC staining of p-AKT in pancreatic cancer tissues of the same ZZU cohort revealed a positive expression correlation between SOX4 and p-AKT (n = 80)." (PMID 33824274, 2021). "We further observed an inverse expression correlation between miR-30d and SOX4 in pancreatic cancer tissues of ZZU cohort." (PMID 33824274, 2021). "Here we demonstrated that miR-30d inhibits pancreatic cancer cell growth and metastasis via targeting the SOX4/PI3K-AKT-signaling pathway." (PMID 33824274, 2021). "To investigate the underlying mechanisms underlying the tumor suppressive function of miR-30d, we examined potential targets of miR-30d by bioinformatics analyses and identified SOX4 as a target gene of miR-30d in pancreatic cancer." (PMID 33824274, 2021). "Overall, these results showed that the expression of SOX4 was increased and correlated with poor patient survival in various cancers, including colon, liver, lung, and pancreatic cancers and sarcoma." (PMID 34442467, 2021). "Although, TGFβ-induced EMT is considered a pro-tumorigenic effect, it becomes lethal in TGFβ-sensitive (SMAD4-wildtype) pancreatic cancer by converting TGFβ-induced Sox4 from an enforcer of tumorigenesis into a promoter of apoptosis." (PMID 31569425, 2019). "Accordingly, we examined the expression levels of miR-129-2, miR-335, and SOX4 in twenty-three paired human pancreatic tumors and normal tissues." (PMID 23251334, 2012). "The pro-oncogenic function of SOX4 in pancreatic cancer is relevant to the control of cell proliferation as evidenced by decreased cell proliferation rates in SOX4-suppressed cells." (PMID 23251334, 2012).
pancreatic cancer (continued). "In conclusion, we disclose a miR-129-2(miR-335)/SOX4/Semaphorin-Plexin regulatory axis in the tumorigenesis of pancreatic cancer." (PMID 23251334, 2012). "We clearly demonstrate that the level of miR-129-2 expression or of miR-335 is inversely correlated with SOX4 expression in most patients with pancreatic cancer in a statistically significant way." (PMID 23251334, 2012). "Instead, our study suggests one possible epigenetic modification mechanism for SOX4 expression in pancreatic cancer via repressed expression level of miR-129-2 and miR-335, which would otherwise target SOX4 transcript at its 3′ UTR for degradation." (PMID 23251334, 2012). "It seems reasonable for pancreatic cancer cells to re-express SOX4 considering that tumor cells often aberrantly re-express developmentally regulated genes for advantageous growth or cell motility." (PMID 23251334, 2012). "Interestingly, TF activity analysis showed that Ep_VGLL1 can be distinguished by the high activities of KLF5 and SOX4, the TF pair marking the tumorigenic SMAD4-deficient pancreatic cancer cells under the TGF-β milieu." (PMID 38297291, 2024). "In vitro cell experiments confirmed that SOX4 promoted IQGAP1 phosphorylation modification by activating MAPK1 transcription while silencing SOX4 inhibited the proliferation, migration, and invasion of pancreatic cancer cells by reducing the phosphorylation level of MAPK1-IQGAP1." (PMID 38943117, 2024). "Mechanistically, the authors delineated a novel circ_0001666/miR-1251/SOX4 regulatory axis in pancreatic cancer cells, whereby the oncogenic effects of circ_0001666 were rescued by miR-1251 overexpression and inhibited SOX4 expression in both in vitro and in vivo experiments." (PMID 35205610, 2022). "This newly identified miR-30d/SOX4/PI3K-AKT axis might represent new promising therapeutic targets for pancreatic cancer." (PMID 33824274, 2021). "Our findings suggest that a combination of miR-30d and SOX4 may help to identify pancreatic cancer patients who need intensive care and early intervention at early stages." (PMID 33824274, 2021). "Combining those data with our own current results, it seems reasonable to assume that SOX4 may have a role in the pathogenesis of pancreatic cancer omental metastasis." (PMID 28632775, 2017). "Collectively, these data indicate that SOX4 could mediate tumor growth via regulation of cell proliferation in pancreatic cancer." (PMID 23251334, 2012). "Our study reveals that the concomitant expression of SEMA3 and Plexin family members is not due to gene amplification but can be partially attributed to increased transcriptional activity driven by an SRY-HMG Box transcription factor SOX4 de novo expressed in pancreatic cancer." (PMID 23251334, 2012). "However, whether SOX4 regulate the growth and invasion abilities of pancreatic cancer cells dependent or independent on PI3K-AKT, and the detailed action mechanism are still needed to be clarified." (PMID 33824274, 2021). "Given the multiple genetic alterations that are present in pancreatic cancer and the minimal physiological effect conferred by the re-expression of miR-129-2 in pancreatic cancer cell lines in vitro, more than one mechanism may contribute to over-expression of SOX4 in pancreatic cancers." (PMID 23251334, 2012). "Thus, we asked whether a hyperactivated RAS/MEK/ERK signal is responsible for SOX4 over-expression in pancreatic cancer." (PMID 23251334, 2012). "Finally, to elucidate the biological significance of SOX4 in pancreatic cancers, Kaplan-Meier survival analysis was performed to demonstrate that SOX4 expression in tissues from human PDAC significantly correlates with shorter survival of patients (P = 0.0409)." (PMID 23251334, 2012). "In vitro experiments using a dual-luciferase reporter assay confirmed that SOX4 binds to MAPK1 and promotes its transcription, establishing the role of the SOX4/MAPK1/IQGAP1 regulatory axis in pancreatic cancer cells." (PMID 41035668, 2025).